TLE3 (TLE family member 3, transcriptional corepressor)
Diseases named in the same sentence as TLE3 in open-access papers (continued):
Sharing a sentence is not in itself a finding about the gene and the disease.
melanoma (continued). "We also confirmed that Tle3 was expressed within the nuclei of B16 murine melanoma cells." (PMID 30719233, 2019). "TLE3 expression was increased during the progression of human patient melanoma (p < 0.05)." (PMID 30719233, 2019). "We then confirmed whether TLE3 was expressed in an additional melanoma cell type." (PMID 30719233, 2019). "We hypothesized that Tle3 may also play role in proliferation of melanoma cells." (PMID 30719233, 2019). "Trichostatin (TSA) is an HDACi, that alleviates the mitogenic effect of Tle3 (transducing-like enhancer of split 3) in both human (HMV-II) and murine (B16) melanoma cell lines." (PMID 35409020, 2022). "More specifically, we show that the TLE3 is enriched during the malignant alteration of melanocytes in human patient tumor samples, and we further present evidence that Tle3 promotes proliferation in murine B16 and human HMV-II melanoma cells by an HDAC activity-dependent mechanism." (PMID 30719233, 2019). "In addition, since TSA treatment reduced the expression of TLE3 (data not shown) it is also possible that the suppressive effect of TSA on the proliferation of melanoma is due to direct HDAC repression of TLE3 expression." (PMID 30719233, 2019).
Obesity (3 papers, 2018 to 2025). Accumulation of substantial excess body fat. "We believe that the elevation in TLE3 protein levels in obesity subjects is partly due to an increase at the transcriptional level, as well as a reduction in protein degradation caused by decreased TRIM56 levels." (PMID 39928840, 2025).
autism (2 papers, 2020 to 2023). Persistent deficits in social interaction and communication and interaction as well as a markedly restricted repertoire of activity and interest as well as repetitive patterns of behavior. "In humans, one de novo TLE3 variant has been reported as potentially causing autism." (PMID 32344861, 2020).
breast tumors (2 papers, 2013 to 2014). "The first acts downstream of beta-catenin influencing microtubule stability, and a previous study indicated that TLE3 expression was associated with improved response to taxane-based therapy in breast tumors." (PMID 23895135, 2013). "To explore the link between ERα status and TLE3 expression in breast tumors, we performed an in silico analysis from publicly available data." (PMID 25223786, 2014).
glioblastoma (2 papers, 2022 to 2023). The most malignant astrocytic tumor (WHO grade IV). "TLE1 and TLE3 are both implicated in cancer; TLE1, for example, promotes glioblastoma propagation and TLE3 stimulates cell division by suppressing myogenic differentiation via transcriptional repression of the master regulator MyoD." (PMID 37260146, 2023).
glioma (2 papers, 2013 to 2022). A benign or malignant brain and spinal cord tumor that arises from glial cells (astrocytes, oligodendrocytes, ependymal cells). "Although having not been reported in glioma-related research, TRIM34, PCGF2, TLE3, and TRIM17 have been revealed to contribute to the carcinogenesis of other cancers." (PMID 35832194, 2022).
lung carcinoma (2 papers, 2022 to 2024). "Additionally, low expression of TLE3 was associated with poor prognosis of FP and OS in lung cancer." (PMID 36451774, 2022).
metastatic disease (2 papers, 2009 to 2022). "In our previous study, IHC of metastatic tumors showed that the percentage of tumors positive for EGFR was higher, and those positive for PTEN and TLE3 were lower in QNBCs compared to TNBCs." (PMID 36550153, 2022).
prostate tumors (2 papers, 2019 to 2022). "TLE3 alternatively spliced isoforms have been detected to be upregulated in prostate tumors, suggesting that the abnormal expression of TLE3 is strongly connected with cancer invasiveness." (PMID 36451774, 2022). "More recently, an alternatively spliced isoform of TLE3 was found to be significantly enriched in prostate tumors." (PMID 30719233, 2019).
sarcoma (2 papers, 2013 to 2021). A usually aggressive malignant neoplasm of the soft tissue or bone. "Transducin-like enhancer 3 (TLE3) is a protein related to the tumorigenesis and classification of sarcomas." (PMID 33802643, 2021). "A major genetic network contains known cancer-related or pro-proliferating genes, including CDC25A, CDK19, FUS (fused in sarcoma), TLE3, and ILF3 (interleukin enhancer binding factor 3) was formed." (PMID 24160375, 2013).
autism spectrum disorder (1 paper, 2020). A spectrum of developmental disorders that includes autism, and Asperger syndrome. "In the patient with a BCT disrupting MLLT10 and TLE3, it is unclear which gene is responsible for the phenotype, nevertheless both genes have few possibly pathogenic variants reported in humans (all linked to autism spectrum disorder) and none of them are similar to the proband phenotype." (PMID 32344861, 2020).
cervical cancer (1 paper, 2022). A primary or metastatic malignant neoplasm involving the cervix. "Numerous researches have reported that TLE3 expression is upregulated in multiple cancers, including cervical cancer and malignant meningiomas." (PMID 36451774, 2022).
COVID-19 (1 paper, 2024). A disease caused by infection with severe acute respiratory syndrome coronavirus 2. "Both genes were also coenriched in the Notch pathway, TLE3, and NCSTN; nonetheless, CTBP1 significantly differed in the COVID-19 comparison group, whereas DTX3L was more significant in the PQ comparison group." (PMID 39301288, 2024). "Four DEPs (RAC1, CAMK2G, DAAM1, and RAC2) were enriched in the noncanonical Wnt pathway and two DEPs (TLE3 and CACYBP) were enriched in the canonical pathway in the COVID-19 comparison group." (PMID 39301288, 2024).
dyslexia (1 paper, 2018). A learning disorder characterized by an impairment in processing written words. "ROBO1, a candidate for dyslexia, is also highly upregulated, whereas, TLE3, a target of FOXP2, is significantly downregulated." (PMID 29922639, 2018).
meningioma (1 paper, 2019). A generally slow growing tumor attached to the dura mater. "Since then, TLE2 and TLE3 have also been shown to be induced during the malignant progression of meningiomas." (PMID 30719233, 2019).
mesothelioma (1 paper, 2022). A usually malignant and aggressive neoplasm of the mesothelium which is often associated with exposure to asbestos. "It should be noted that all cases of genetically altered mesothelioma (more than 3% frequency) had amplification of TLE3." (PMID 36451774, 2022).
ovarian tumors (1 paper, 2020). "Furthermore, we examined TLE3 and LOC642852 expression in pools of OC samples from ovarian tumors, omental/peritoneal metastases, and effusions." (PMID 32718068, 2020).
rheumatoid arthritis (1 paper, 2022). A chronic, systemic autoimmune disorder characterized by inflammation in the synovial membranes and articular surfaces. "Although the underlying mechanism is elusive, our ChIPEA suggested that LEF suppresses tumor growth by activating TLE3 and inactivating RELA and E2F1, possibly via the same mechanisms involved in rheumatoid arthritis treatment." (PMID 35073843, 2022).
sarcoidosis (1 paper, 2022). Sarcoidosis is a multisystemic disorder of unknown cause characterized by the formation of immune granulomas in involved organs. "Notably, we previously identified TLE3 among the predicted targets of hsa-miR-22-5p, hsa-miR-30e-3p, and hsa-miR-4306 within a diagnostic and prognostic micro-RNA signature associated with sarcoidosis immune dysregulation." (PMID 36311769, 2022). "The TLE3 and CBX8 PLS-DA models were further parsed to identify target genes in the MAM cell death subnetwork most likely associated with the characteristic imbalance of PBMC proportions observed in sarcoidosis." (PMID 36311769, 2022). "Selectively targeting and modulating CBX8 and TLE3 activity may represent a promising novel strategy for management of sarcoidosis." (PMID 36311769, 2022).
spastic diplegia (1 paper, 2020). A type of cerebral palsy characterized by spasticity and hypertonia of the lower extremities bilaterally, particularly the legs, hips, and pelvis; this is the most common (70%) form of cerebral palsy. "Interestingly, CTNNB1 (MIM: 116806) has been linked to autosomal dominant neurodevelopmental disorder with spastic diplegia and visual defects (MIM: 615075), making TLE3 an even more plausible candidate for impacting the patient phenotype." (PMID 32344861, 2020).
triple-negative breast carcinoma (1 paper, 2017). An invasive breast carcinoma which is negative for expression of estrogen receptor (ER), progesterone receptor (PR), and human epidermal growth factor receptor 2 (HER2). "Patients with TLE3-negative tumors displayed significantly poorer outcomes regarding progression-free survival than patients with TLE3-positive tumors when prognosis within the group of patients with triple-negative breast cancer (TNBC) lesions was analyzed (p = 0.011, log-rank)." (PMID 28859615, 2017).
type 2 diabetes (1 paper, 2024). "Subcutaneous adipose tissue TLE3 is increased in type 2 diabetes and decreased in bariatric surgery-induced weight loss." (PMID 39351529, 2024). "In humans, TLE3 expression in subcutaneous adipose tissue is increased in type 2 diabetes and decreased following bariatric surgery-induced weight loss." (PMID 39351529, 2024).
uterine tumor (1 paper, 2022). "The frequency of alteration in TLE3 was the highest (>4%) in patients with a “mutation” primary type of uterine tumor." (PMID 36451774, 2022).
tumor (20 papers, 2009 to 2025). "In brief, our study showed that TLE3 was high-expressed in the majority of cancers, had different prognostic effects in various tumor cases, and was associated with the progression of OV." (PMID 36451774, 2022). "The top 100 genes associated with TLE3 expression were obtained from all tumor expression data from TCGA using the GEPIA2 tool." (PMID 36451774, 2022). "The current work provided the first comprehensive investigation of TLE3 in a pan-cancer study, highlighting the role of TLE3 in the tumor immune microenvironment, and also determined the potential of TLE3 as a prognostic, immunotherapy response, and diagnostic biomarker in many cancers." (PMID 36451774, 2022). "Comprehensive analysis of TCGA, GEO, and GTEx data with an online tool, and R language was performed to explore the relationship of TLE3 expression between prognosis, gene mutation, protein phosphorylation, DNA methylation, tumor microenvironment, and related pathways in 33 tumors." (PMID 36451774, 2022). "In addition, retrospective review of tumor response to treatment showed a significant association between TLE3 expression and decrease in tumor size after neoadjuvant treatment." (PMID 19309506, 2009). "In bivariable analysis with TLE3+, only tumor size trended toward an independent association with outcome in taxane-treated patients whereas age, node status, pathologic grade, and Ki67 and epidermal growth factor receptor (EGFR) expression were not significant." (PMID 19309506, 2009). "Tumor size reduction was highly correlated with likelihood of recurrence at 5 years (HR = 1.56, P = 0.0001), and a significant association between staining with TLE3 and decrease in tumor size was confirmed (t test one-sided P value < 0.04)." (PMID 19309506, 2009). "We explored the immune characteristics of TLE3 in the tumor microenvironment (TME), including tumor-infiltrating lymphocytes, immunostimulatory factors, MHC molecules, chemokines, receptors, and immune checkpoints." (PMID 36451774, 2022). "TLE3 was high-expressed in most tumors, and TLE3 expression and the prognosis of some tumor types were significantly correlated." (PMID 36451774, 2022). "(D) Immunohistochemistry for H and E, TLE3 and GR in tumor biopsy samples collected from two CRPC patients pre- and post-enzalutamide treatment." (PMID 31855178, 2019). "in vivo injection of mice with B16 cells overexpressing Tle3 resulted in larger tumor formation than in mice injected with control cells (p < 0.05)." (PMID 30719233, 2019). "Based on a univariate analysis of 22 TNBC cases, a better progression-free survival correlated significantly with a positive TLE3 expression in the tumor (p = 0.025)." (PMID 28859615, 2017). "Based on a univariate analysis of 22 TNBC cases, a better PFS correlated significantly with a positive TLE3 expression in the tumor (p = 0.025)." (PMID 28859615, 2017). "Of the eleven core biopsy samples for which tumor material was apparently completely depleted by neoadjuvant therapy, seven were TLE3+ and only one of these seven ultimately recurred." (PMID 19309506, 2009). "In terms of the tumor microenvironment, TLE3 affected a wide variety of cancers, especially PRAD and LIHC, and TLE3 may act on them via immune-related pathways." (PMID 36451774, 2022). "Both TLE3 and the tumor suppressor DACH1 are negative regulators of Wnt signaling." (PMID 34795231, 2021). "Our preliminary data showed that over-expression of Tle3 reduced the number of apoptotic B16 cells induced by TSA treatment (data not shown), indicating that the reduction of apoptosis by Tle3 may be involved in the regulation of B16 tumor size by Tle3." (PMID 30719233, 2019). "Finally, we demonstrated the clinical relevancy of Tle3 as a therapeutic target by showing that Tle3 knockdown led to a significant reduction in tumor size in vivo." (PMID 30719233, 2019).
tumor (continued). "Additionally, immunohistochemistry on GR and TLE3 of tumor tissue collected from CRPC patients pre- and post-enzalutamide treatment support our findings in LNCaP cells." (PMID 31855178, 2019). "Therefore, TLE3 expression in the tumor was identified to be an independent predictive marker of the therapeutic effect of eribulin chemotherapy among patients with TNBC lesions." (PMID 28859615, 2017). "Since our results indicate that TLE3 is an important regulator of ERα basal transcription, a disturbance in its repressive function could favor tumor development and hormone-therapy resistance." (PMID 25223786, 2014). "While these data are exploratory and do not incorporate more recent quantitative methods of measuring tumor response, the possibility of using TLE3 as tool to predict response in the neoadjuvant setting is intriguing and warrants further study in a prospective trial." (PMID 19309506, 2009). "Moreover, the TLE3 expression was positively related to a large number of immune checkpoint genes in many cancers, especially KIRC, BRCA, and LAML, suggesting that TLE3 participated in the tumor immune response regulation through modulating immune checkpoint activity." (PMID 36451774, 2022). "Therefore, we also observed the state of TLE3 genetic alteration in different tumor samples." (PMID 36451774, 2022). "Besides, TLE3 upregulation may also induce cell cycle arrest and tumor growth suppression via inhibition of MAPK and AKT pathways." (PMID 34539626, 2021). "Transducin-like enhancer of split 3 (TLE3), a member of the TLE gene family, is related to tumor genesis and progression." (PMID 36451774, 2022). "In colorectal cancer, high RNF6 expression promotes tumor cell proliferation and metastasis, and the effect is related to RNF6-mediated TLE3 ubiquitination and degradation, followed by increased Wnt pathway activation." (PMID 36438567, 2022). "Normal tissue data from the GTEx dataset were used as a control, we further evaluated the difference in TLE3 mRNA expression between LGG control tissues and tumor tissues (P < 0.05)." (PMID 36451774, 2022). "Normal breast, colon, lung, and prostate TLE3 IHC staining of tissues were negative or moderate, while that of tumor tissues were moderate or strong." (PMID 36451774, 2022). "Tumor tissue of these patients showed moderate to high GR expression at baseline with weak or negative staining for TLE3." (PMID 31855178, 2019). "TLE3 was independent of tumor size, nodal status, and grade by bivariable analysis in both cohorts." (PMID 19309506, 2009).
cancer (14 papers, 2013 to 2024). A tumor composed of atypical neoplastic, often pleomorphic cells that invade other tissues. "To further study the TLE3 effect on immunological status in pan-cancers, we analyzed the association between its mRNA expression and the immunomodulators in 33 cancer types using the TISIDB database." (PMID 36451774, 2022). "Analysis of TLE3 correlation with checkpoint gene expression in pan cancers showed that Tle3 was closely linked to CD276." (PMID 36451774, 2022). "The level of TLE3 expression in 33 cancer types was closely associated with DNA methylation." (PMID 36451774, 2022). "Additionally, three immunotherapeutic biomarkers (TMB, MSI, and MMR) were found to be significantly associated with TLE3 in some cancers." (PMID 36451774, 2022). "Furthermore, the impact of TLE3 gene mutations on survival in pan-cancer was also studied." (PMID 36451774, 2022). "In conclusion, TLE3 played an important and dual role (both inhibition and promotion) in pan-cancer immune infiltration." (PMID 36451774, 2022). "KEGG and GO enrichment and GSEA analysis of BRCA and LIHC also confirmed the correlation between TLE3 and the immune microenvironment, suggesting the significance of TLE3 in the immunity of a variety of cancers." (PMID 36451774, 2022). "TLE3 was positively associated with most of the immunomodulators of LIHC, indicating that LIHC was a candidate cancer type suitable for TLE3 immunotherapy." (PMID 36451774, 2022). "TLE3 also regulates metabolism and cell fate in the bone, pancreas, muscle, embryonic stem cell, and cancer." (PMID 31569653, 2019). "Therefore, based on the CPTAC dataset, we determined the TLE3 protein expression levels in 33 cancers." (PMID 36451774, 2022). "We applied TIMER2 to explore the TLE3 mRNA expression across 33 cancers." (PMID 36451774, 2022). "The implication of these results was that high-level phosphorylation sites of Tle3, such as S267 and S217, may promote cancers and it should be further explored." (PMID 36451774, 2022). "According to our results, the TLE3 protein had a conserved structure in various species, indicating that effects of TLE3 may exist with similar mechanisms between these species, hence, it could be viable to use mice for studying TLE3-related cancer in humans." (PMID 36451774, 2022). "As TLE3 was overexpressed in pan-cancer, we further explored its prognostic profile." (PMID 36451774, 2022). "Moreover, Enriched Map by Cytoscape Software also showed “Pathway in cancer,” pointing to the close potential relationship between TLE3 and cancers." (PMID 36451774, 2022). "Taken together, these results suggest that TLE3 may still be expressed in cancer cells because of its dual role in transcription." (PMID 25223786, 2014). "High-level phosphorylation sites of Tle3, such as S267 and S217, may promote cancers." (PMID 36451774, 2022). "However, whether TLE3 played a crucial role in the whole pan-cancer remained unknown." (PMID 36451774, 2022). "RING-type E3 ubiquitin transferase (RNF6) is known for its ubiquitination of various substrates, including the androgen receptor (AR), transducin-like enhancer of split 3 (TLE3) and the tyrosine phosphatase, SHP-1, in order to mediate the proliferation of various types of cancer cells." (PMID 34685511, 2021). "Thus, in absence of TLE3, cells could be more prone to inappropriate gene expression, leading to uncontrolled proliferation and, possibly, to cancer development." (PMID 25223786, 2014). "However, TLE3 has previously been studied in only a few cancer types, its role in other types of cancer remains unclear, and the pathogenesis or impact on the survival of different cancers has not been elucidated." (PMID 36451774, 2022).
infection (1 paper, 2025). The state of being infected such as from the introduction of a foreign agent such as serum, vaccine, antigenic substance or organism. "Notably, 12 of these TFs exhibited distinct phosphorylation patterns upon infection, including MED14, SIN3A, BCL6, cJUN, NFATC1, STAT3, RUNX3, GTF2F1, MED1, JUNB, TLE3, and FOSL2." (PMID 40368139, 2025).